INS (insulin)
Diseases named in the same sentence as INS in open-access papers (continued):
Sharing a sentence is not in itself a finding about the gene and the disease.
type 1 diabetes (continued). "Because of the pivotal role of insulin in lipoprotein metabolism, poor glycaemic control in type 1 diabetes is associated with high levels of atherogenic triglyceride-rich lipoproteins as well as cholesterol-rich LDL particles." (PMID 38032368, 2023). "Type 1 diabetes (T1D) is a progressive autoimmune disease characterized by T-cell-mediated dysfunction and loss of insulin-producing β cells." (PMID 37792778, 2023). "Type I Diabetes mellitus is a severe autoimmune disease caused by disruption of insulin-producing pancreatic β-cells." (PMID 36911193, 2023). "Type 1 diabetes is caused by the inability of the pancreatic beta cells to produce sufficient amounts of insulin, an anabolic hormone promoting the absorption of the blood glucose by various cells in the body, primarily hepatocytes and skeletal muscle cells." (PMID 36676521, 2023). "Type 1 diabetes is characterized by autoimmune loss of pancreatic beta cell mass leading to metabolic dysregulation, requiring lifelong insulin therapy." (PMID 36314991, 2023). "Type 1 diabetes (T1D) is one of the most common autoimmune diseases in children and is caused by destruction of the insulin producing beta-cells in the pancreas." (PMID 38102669, 2023). "Other researchers have investigated factors associated with HbA1c in type 1 diabetes; however, often focus has been on relatively few factors per study, and study samples have often consisted of both people treated with insulin injections and insulin pumps." (PMID 37160785, 2023). "Type 1 diabetes (T1D) is an autoimmune disease characterized by the loss of pancreatic beta cells that secrete insulin." (PMID 37875949, 2023). "Type 1 diabetes (T1D), also known as “juvenile/childhood-onset diabetes,” is a serious, life-long autoimmune condition characterized by deficiency of insulin production." (PMID 36767047, 2023). "We postulate that a defect in insulin secretion is secondary to disrupted autophagy and would predispose beta cells to the autoimmune destruction that causes type 1 diabetes." (PMID 37175930, 2023). "Among them, type 1 diabetes is caused by the destruction of pancreatic beta cells, insufficient insulin secretion, leading to hyperglycemia and even ketosis." (PMID 36761194, 2023). "Type 1 diabetes, a disorder caused by autoimmune destruction of pancreatic insulin-producing cells, is more difficult to manage when it presents at a younger age." (PMID 36817429, 2023). "Type 1 diabetes (T1D) is characterized by a chronic inflammatory response associated with the autoimmune destruction of insulin-producing beta cells in the pancreas." (PMID 37296628, 2023). "Up to 40% of young women with type 1 diabetes report insulin omission with the purpose of weight loss." (PMID 36754894, 2023). "Type 1 diabetes patients carrying a ‘protective’ insulin gene (INS) variant present a disease endotype with reduced insulin antibody titers, preserved beta cell function and improved glycemic control." (PMID 36701305, 2023). "The loss of insulin production capacity in type 1 diabetes has long been considered the inevitable consequence of the complete destruction of pancreatic beta cells through a targeted cytotoxic autoimmune attack." (PMID 36394644, 2023). "Idiopathic loss of endogenous insulin secretion is also defined as type 1 diabetes in some international definitions." (PMID 36778553, 2023). "It was initially thought that the alpha cell becomes dysregulated only in later stages of type 1 diabetes when loss of beta cell mass (leading to deficient insulin and unrestrained somatostatin secretion) perturbs paracrine modulation of glucagon release." (PMID 37488322, 2023). "Type 1 diabetes (T1D) is a chronic metabolic disease caused by the autoimmune destruction of insulin-secreting pancreatic β-cells, which causes serious chronic complications and irreversible multiple organ damage to patients." (PMID 37175774, 2023).
type 1 diabetes (continued). "Type 1 diabetes is caused by impaired insulin production by pancreatic β-cells and a daily insulin injection is required to keep blood glucose level within an appropriate range." (PMID 37905438, 2023). "This study focused on outpatient children with Type 1 Diabetes (T1D), in which there is a substantial risk of medication errors that can result in dangerous under- or overdosing of insulin." (PMID 38571735, 2023). "For instance, increased pro-insulin levels have been described as an early indication of beta cell loss in human type 1 diabetes." (PMID 36614300, 2023). "Type 1 diabetes (T1D) is characterized by progressive loss of pancreatic β cell function that leads to lifelong dependence on insulin therapy." (PMID 37789144, 2023). "Some characteristics, such as younger age, type 1 diabetes, and treatment with insulin, seem to be more strongly associated with HbF expression." (PMID 37296725, 2023). "By contrast, type 1 diabetes is caused by autoimmune attack upon pancreatic β-cells, causing an almost complete loss of insulin production and secretion." (PMID 37240215, 2023). "Type 1 diabetes (T1D) is a chronic autoimmune disease featured by the loss of beta cell function and the need for lifetime insulin replacement." (PMID 37229215, 2023). "In TRIALNET participants who were diagnosed with islet-autoantibody-positive type 1 diabetes up to the age of 45 years, insulin loss was largely unaffected by onset age in children, but in adult-onset cases, insulin loss was less rapid." (PMID 37728732, 2023). "In conclusion, the relative differences in the treatment effect of insulin analogs in people with type 1 diabetes at increased risk of hypoglycemia are comparable to those observed in low risk populations in phase III trial." (PMID 38089060, 2023). "Type 1 diabetes (T1D) is an immune-mediated disease characterized by the progressive loss of insulin-producing β-cells in the islets of Langerhans within the pancreas." (PMID 38034007, 2023). "Type 1 diabetes (T1D) is characterized by hyperglycemia, which results from an insulin deficit caused by the autoimmune destruction of pancreatic beta cells." (PMID 37900142, 2023). "Some studies have reported much higher levels of retained endogenous insulin secretion than in type 1 diabetes elsewhere, with lower rates of type 1 diabetes genetic susceptibility and HLA haplotypes." (PMID 36778553, 2023). "Type I diabetes is a chronic autoimmune disease characterized by the loss of insulin-producing β cells in the pancreas, leading to insulin deficiency." (PMID 37108202, 2023). "People with type 1 diabetes (T1D) are particularly susceptible to hypoglycemia due to the use of exogenous insulin and the loss of hypoglycemia-induced glucagon secretion." (PMID 37788058, 2023). "Type-1 diabetes mellitus (T1DM) is a chronic disorder characterized by a deficiency in insulin production." (PMID 40303265, 2023). "Increases in the abundance of many classes of lipids were common in all analyses performed, likely to be caused by insufficient insulin availability, the key pathophysiological feature of type 1 diabetes." (PMID 37615689, 2023). "Are different glucose monitoring and insulin delivery modalities associated with the achievement of recommended continuous glucose monitoring (CGM) targets in youths with type 1 diabetes?" (PMID 36808243, 2023). "STZ is known to selectively destroy insulin-producing beta cells in the pancreas, resulting in insulin deficiency and the development of type 1 diabetes." (PMID 37629045, 2023). "Type 1 diabetes mellitus (T1D) is a chronic metabolic disease precipitated by an immune-associated destruction of insulin-producing β-pancreatic cells." (PMID 37951886, 2023). "Type-1 diabetes is characterized by insulin deficiency due to the destruction of pancreatic β cells, while T2D is associated with a gradual loss of insulin secretion." (PMID 36771665, 2023).
type 1 diabetes (continued). "Type 1 diabetes is characterized by insulin deficiency, and treatment is to supply insulin mimicking the physiological endogenous insulin secretion." (PMID 38089060, 2023). "Severe insulin deficiency not only is a biomarker of type 1 diabetes but also, by definition, indicates a need for insulin replacement, thereby linking treatment to pathogenesis." (PMID 35994083, 2022). "Type 1 diabetes (T1D) is an autoimmune disease that results in loss of insulin-making beta cells in the pancreas, which significantly affects the maintenance of blood glucose, both at rest and during physical activity." (PMID 36992764, 2022). "Type 1 diabetes is caused by genetics and immunity to destroy a large number of β cells, and insulin secretion is absolutely insufficient, which is more prone to microvascular complications." (PMID 35242879, 2022). "We aimed to define the prevalence of LH and identify its risk factors in type 1 diabetes (T1DM) patients treated with continuous subcutaneous insulin infusion (CSII)." (PMID 35111222, 2022). "As the β-cell population drops, the absolute deficiency of available insulin to maintain the normal blood glucose level develops, and type 1 diabetes is mainly diagnosed in children and young adults." (PMID 36144750, 2022). "In summary, our study shows that only a minority of patients with type 1 diabetes in China utilize insulin pump therapy, which is associated with better blood glucose control and self-management." (PMID 35757419, 2022). "Type 1 diabetes results from the immunological destruction of pancreatic β cells and the subsequent loss of insulin secretion leads to dysregulated blood glucose levels." (PMID 36550929, 2022). "Insulin secretion from β-cells is reduced in type I diabetes, leading to a deficiency of glucose and glycogen levels in the liver." (PMID 35736457, 2022). "DPP-4is combined with vitamin D3 can delay the loss of β cells and improve endogenous insulin production in patients with new-onset type 1 diabetes and LADA." (PMID 35992113, 2022). "Type 1 diabetes is characterized by an autoimmune β-cell destruction that leads to absolute insulin deficiency and permanent reliance on exogenous insulin." (PMID 35757419, 2022). "Type 1 diabetes (T1D) is an autoimmune disease caused by selective immune-mediated destruction of β-cells, requiring lifelong insulin therapy." (PMID 34927076, 2022). "In pregnant women with type 1 diabetes with elevated fasting C-peptide levels, the insulin dose should be diminished to reduce the risk of hypoglycemia." (PMID 35207323, 2022). "Joslin and Benedict observed in 1912 that the metabolic rate in insulin-deficient states (i.e., type 1 diabetes) is significantly higher than expected—a phenomenon subsequently shown to be correctable with administration of insulin." (PMID 35177807, 2022). "Type 1 diabetes (T1D) is an autoimmune disorder causing pancreatic β-cell loss that results in progressive failure of insulin secretion to control blood glucose levels." (PMID 36726462, 2022). "Insulin bolus administration frequency is strongly associated with glycated hemoglobin (A1c) in Type 1 Diabetes (T1D)." (PMID 36100854, 2022). "Higher resistin levels were also observed in a group of children and adolescents with type 1 diabetes compared to healthy controls, supporting that resistin is associated with insulin metabolism discrepancies." (PMID 36360347, 2022). "In accordance with the American Diabetic Association 2022 guidelines, insulin administration is the primary treatment for type 1 diabetes." (PMID 36012526, 2022). "Type I diabetes (T1D) is a complex autoimmune disorder characterized by insulin deficiency resulting from autoimmune destruction of insulin-secreting pancreatic β-cells in genetically predisposed individuals." (PMID 35419034, 2022).
type 1 diabetes (continued). "This cross-sectional study aims to evaluate the prevalence of insulin-induced lipodystrophy in a cohort of pediatric patients with type 1 diabetes, to identify associated clinical factors and to assess its influence on glycemic control." (PMID 35884071, 2022). "Type 1 diabetes (T1D) is caused by the autoimmune-mediated destruction of insulin-producing beta-cells." (PMID 35326375, 2022). "In this study of 284 females and 304 males with type 1 diabetes, we found that the longitudinal insulin regimen pattern was associated with different trends in eBFP throughout youth and into young adulthood for females." (PMID 35127949, 2022). "When interpreting the results, it is also worth remembering the reduced amounts of endogenous insulin and C-peptide in type 1 diabetes, which can cause the results to have a lower diagnostic value." (PMID 35324747, 2022). "Our results further confirm the contribution of metabolic factors to AN etiology; we see very robust association of AN-GReX with type 1 diabetes, the hyperglycemic hormone glucagon and various forms of insulin." (PMID 35379376, 2022). "These criteria are less restrictive than eligibility to insulin pumps, which were also found to be associated with improved glycaemic outcomes among people with type 1 diabetes in Scotland." (PMID 34618177, 2022). "Type 1 diabetes (T1D) is a metabolic syndrome caused by the loss of autoimmune tolerance to insulin-producing islet β-cells." (PMID 36405706, 2022). "Type 1 diabetes is caused by progressive loss of the insulin-producing beta cells in pancreatic islets." (PMID 35867130, 2022). "Type-1 diabetes is a condition in which blood sugar levels rise due to a shortage of insulin, causing problems with the blood sugar metabolism." (PMID 36236367, 2022). "PTPRN encodes islet antigen 2 (IA-2), a major type 1 diabetes autoantigen involved in glucose-stimulated insulin secretion." (PMID 35763030, 2022). "Type 1 diabetes (T1D) is a multifactorial autoimmune disease driven by T-cells against the insulin-producing islet β-cells, resulting in a marked loss of β-cell mass and function." (PMID 36498975, 2022). "Type 1 diabetes is a consequence of impaired insulin production due to a loss of pancreatic β cells." (PMID 36145160, 2022). "Type 1 diabetes mellitus (T1D), a chronic disease caused by destruction of pancreatic cells and decreased insulin secretion, is accompanied by various complications, and has serious effects on the quality of life and life span." (PMID 36619558, 2022). "In the case of type 1 diabetes (T1D), a reduction of Treg cell function contributes to unrestrained immune destruction of the insulin-generating pancreatic beta cells, resulting in the loss of control of blood sugar levels." (PMID 35773720, 2022). "A case report showed that JAK1/JAK2 inhibitor ruxolitinib normalized blood-glucose levels and discontinued exogenous insulin in a patient with type 1 diabetes caused by STAT1 gain-of-function." (PMID 35242127, 2022). "Type 1 diabetes (T1D) is an autoimmune disease caused by the immune system attacking and destroying insulin-producing β cells in the pancreas." (PMID 35903090, 2022). "Type 1 diabetes (T1D) is caused by the T cell-driven autoimmune destruction of insulin-producing cells in the pancreas." (PMID 35464420, 2022). "Type 1 diabetes (T1D) is caused by immune-mediated destruction of the insulin-producing β-cells resulting in a life-long insulin dependence." (PMID 35464488, 2022). "In this context, gastric emptying should have major implications (which remain to be evaluated) for algorithms relating to the optimal use of insulin pumps linked to real time subcutaneous glucose monitoring systems in type 1 diabetes." (PMID 36194250, 2022). "Type 1 diabetes mellitus (T1DM) is an autoimmune disease caused by the destruction of insulin-producing beta cells." (PMID 35729640, 2022).
type 1 diabetes (continued). "Spontaneous mutation in the insulin two gene leads to incorrect folding of the insulin proteinMonogenic mouse model for type 1 diabetes." (PMID 35188462, 2022). "The most frequent cause-effect is “unable to afford insulin,” which causes “death” expressed in 1246 cases, followed by “insulin” causing “death” with 1156 cases and “type 1 diabetes” causing “fear” with 1054 cases." (PMID 35852829, 2022). "This suggests that in type 1 diabetes, islet β-cell transdifferentiation is involved in the loss of INS secretion function." (PMID 36467676, 2022). "Recent work has also implicated peptide processing that leads to hybrid-insulin peptide formation, generating a neoepitope as etiologic in type 1 Diabetes." (PMID 36090990, 2022). "For example, type 1 diabetes is a result of the loss of insulin-producing beta cells in the pancreas, but recent studies have successfully reprogrammed these cells from pancreatic alpha cells, essentially curing type 1 diabetes in mice." (PMID 35411370, 2022). "An absolute deficiency of insulin secretion characterizes Type-1 diabetes, so they need insulin substitutes." (PMID 35204283, 2022). "Over 1 million children and adolescents have type 1 diabetes (T1D), a disease caused by an autoimmune reaction against the insulin-producing beta cells in the pancreatic islets." (PMID 35986039, 2022). "Type 1 diabetes results from the loss of pancreatic β cells, reduced insulin secretion and dysregulated blood glucose levels." (PMID 36550929, 2022). "Determinants of blood glucose trajectories in the first year of life included sex, body mass index, glucose-related genetic risk scores, and the type 1 diabetes–susceptible INS gene." (PMID 36250461, 2022). "Although intensive insulin therapy has been proven to reduce the incidence of micro- and macrovascular complications of type 1 diabetes, its use is unfortunately associated with weight gain as a side effect of therapy." (PMID 35784568, 2022). "Insulin/C-peptide deficiency in type 1 diabetes is an essential factor in the pathogenesis of CNS dysfunction." (PMID 36359305, 2022). "Type 1 diabetes mellitus (T1DM) is a chronic disease characterised by insulin deficiency due to autoimmune destruction of insulin-producing β-cells within the pancreatic islets." (PMID 36578059, 2022). "Type 1 diabetes (T1D) is an autoimmune disorder characterized by T-cell mediated insulin-producing beta cell loss leading to insulin deficiency and unregulated blood glucose levels." (PMID 36351917, 2022). "Type 1 diabetes (T1D) is an autoimmune disease caused by immune cell destruction of the insulin-producing beta cells in the pancreatic islets." (PMID 36527134, 2022). "Type 1 diabetes (T1D) results from loss of the insulin-producing beta cells in the endocrine pancreas by a process referred to as autoimmunity." (PMID 36291653, 2022). "Type 1 Diabetes (T1D) is a common chronic disorder, caused due to the destruction of insulin-producing pancreatic beta cells." (PMID 35327689, 2022). "This concept has particular appeal for type 1 diabetes, a condition in which the loss of approximately 0.8 g of pancreatic β cells results in a lifelong need for insulin injections." (PMID 35104802, 2022). "Patients with type 1 diabetes should practise regular physical activity, as it reduces the risk of developing cardiovascular diseases and significantly decreases their insulin requirements." (PMID 35577814, 2022). "This study aimed to assess real-life ISF among children and adolescents with type 1 diabetes using ultra-long-acting basal insulin analogs and to detect factors associated with ISF among those patients." (PMID 35350271, 2022). "Exogenous insulin represents the predominant treatment modality for type 1 diabetes, but is associated with long-term complications." (PMID 35222280, 2022).